OR2T11 (olfactory receptor family 2 subfamily T member 11)
Description:
Odorant receptor.
Synonyms: OR2T11Q
Tractability: Antibody: UniProt places it where antibodies can reach, with medium confidence; UniProt predicts a signal peptide or a membrane-spanning region; its Gene Ontology location is reachable by antibodies, with medium confidence.
Gene: Protein-coding gene on chromosome 1 (248,623,557 to 248,635,091, reverse strand). Ensembl gene ENSG00000279301.
Subcellular location: Cell membrane
Pathways (Reactome):
Sensory Perception: Expression and translocation of olfactory receptors
Gene Ontology:
Molecular function: olfactory receptor activity; G protein-coupled receptor activity
Biological process: detection of chemical stimulus involved in sensory perception of smell; G protein-coupled receptor signaling pathway
Cellular component: plasma membrane; membrane
Genetic constraint (gnomAD): Loss-of-function variants: 14 observed, 12.96 expected, observed/expected ratio (o/e) 1.08, 90% interval 0.71 to 1.66. The upper end of that interval is the gene's LOEUF score, 1.66, which puts it in group 6 of 6, group 1 being the genes least tolerant of losing a copy. Missense variants: 397 observed, 384.61 expected, observed/expected ratio (o/e) 1.03, 90% interval 0.95 to 1.12. Synonymous variants: 157 observed, 153.48 expected, observed/expected ratio (o/e) 1.02, 90% interval 0.9 to 1.17.
Homologues: Orthologues: chimpanzee OR2T11 (97% identical), dog OR2T11 (89% identical), rabbit OR2T11 (83% identical). Paralogues in human: OR2T2 (69% identical), OR2T35 (69% identical), OR2T27 (65% identical), OR2T1 (64% identical), OR2T29 (63% identical), OR2T5 (63% identical), OR2T4 (62% identical), OR2T6 (61% identical), OR2T10 (56% identical), OR2T3 (55% identical), OR2T34 (54% identical), OR2M2 (52% identical), and 80 more.